PCAT19 (prostate cancer associated transcript 19)
Diseases named in the same sentence as PCAT19 in open-access papers (continued):
Sharing a sentence is not in itself a finding about the gene and the disease.
heart failure (1 paper, 2022). Inability of the heart to pump blood at an adequate rate to meet tissue metabolic requirements. "Other lncRNAs, including SNHG29 and PCAT19, have not been investigated in heart failure contexts, but they are known as potential regulators in cell signaling pathways." (PMID 35415316, 2022).
hemangioma (1 paper, 2022). A benign vascular lesion characterized by the formation of capillary-sized or cavernous vascular channels. "It was therefore interesting to find a significant and marked reduction in PCAT19 expression in hemangioma samples." (PMID 36384122, 2022).
tumor (19 papers, 2020 to 2025). "The diagnostic potential of PCAT19 is significant, characterized by its differential expression between tumor and normal tissues, rendering it a valuable biomarker for cancer diagnosis." (PMID 39744012, 2024). "In the cytoplasm, PCAT19 functions as ceRNA by sponging miR-429, a prominent tumor suppressor miRNA implicated in various cancers, including GC." (PMID 39744012, 2024). "The expression of PCAT19 was negatively correlated with tumor grade, histological grade, and tumor mutation load in LUAD." (PMID 35095999, 2021). "The results showed that PCAT19 expression and tumor mutation burden were also significantly negatively correlated, indicating that the lower the PCAT19 expression in LUAD tumor cells, the higher the number of mutations contained (p < 0.05)." (PMID 35095999, 2021). "In vivo studies using a mouse xenograft model corroborated these findings, showing that PCAT19 knockdown leads to smaller tumor volumes and reduced expression of proteins associated with cell survival and invasion, such as Survivin, Bcl-2, and MMP-9, while increasing pro-apoptotic Bax levels." (PMID 39744012, 2024). "In addition, the expression of PCAT19 was also negatively correlated with the tumor mutational burden of LUAD." (PMID 35095999, 2021). "In addition, we analyzed the relationship among PCAT19 expression, immune neoantigens, tumor mutational burden, and microsatellite instability in LUAD." (PMID 35095999, 2021). "In contrast, studies involving other NSCLC cell lines (such as A549, SK-MES-1 and SPC-A1) indicate a tumor-suppressive role for PCAT19." (PMID 39744012, 2024). "This reduced binding leads to a decrease in the expression of the tumor-suppressing PCAT19-short and an increase in the oncogenic PCAT19-long, promoting cell proliferation and tumor growth through interaction with HNRNPAB." (PMID 38249783, 2024). "In vivo xenograft tumor models further confirmed that PCAT19 knockdown significantly reduces tumor growth, increases miR-182 levels, and decreases PDK4 expression and PDHE1α phosphorylation." (PMID 39744012, 2024). "PCAT19 not only serves as a biomarker for tumor prognosis and diagnosis but also offers potential as a therapeutic target, making it a focal point in cancer research and treatment strategies." (PMID 39744012, 2024). "In GC, higher PCAT19 expression significantly correlates with larger tumor size, lymphatic metastasis, and advanced TNM stage." (PMID 39744012, 2024). "PCAT19 exhibits a dual nature, functioning either as an oncogene or a tumor suppressor, depending on the cancer type." (PMID 39744012, 2024). "Mechanistically, PCAT19 plays a crucial role in tumor progression by acting as a competitive endogenous RNA (ceRNA)." (PMID 39744012, 2024). "This downregulation indicates a different role of PCAT19 in these cancers, possibly acting as a tumor suppressor." (PMID 39744012, 2024). "Across different cancer types, PCAT19 exhibits a consistent pattern of altered expression, strongly correlated with tumor progression and patient outcomes." (PMID 39744012, 2024). "In concordance with this finding, PCAT19 was significantly downregulated in tumor samples and expressed higher in patients with lower tumor grade, clinical stage, and better lymph node status." (PMID 36992525, 2023). "Above all, we found that PCAT19 exerted tumor‐suppressing ability by inhibiting cancer cell proliferation in vitro and in vivo." (PMID 36992525, 2023). "MicroRNAs (miRNA) negatively correlated with PCAT19 (miR‐210, miR‐331, miR‐324, miR‐769, miR‐33a, miR‐301a, miR‐1301, and miR‐33b) and six tumor‐suppressing genes were introduced to the construction of ceRNA network." (PMID 36992525, 2023). "The PCAT19‐related genes were enriched in signaling pathways involved in tumor development, indicating PCAT19 was an essential regulator of BC." (PMID 36992525, 2023). "Consistent with the results of the proliferation assay in vitro, overexpression of PCAT19 reduced tumor growth in vivo." (PMID 36992525, 2023).
tumor (continued). "The results showed that higher PCAT19 expression was significantly correlated with larger tumor size (P = 0.041), lymphatic metastasis (P = 0.009), and TNM stage (P = 0.005)." (PMID 34976174, 2022). "We also analyzed the correlation between PCAT19 and clinicopathologic characteristic of GC patients, and the results confirmed that a higher PCAT19 expression is related to larger tumor size, lymphatic metastasis, and TNM stage." (PMID 34976174, 2022). "The expression of PCAT19 was decreased in LC tissues and related to patient survival, tumor size, and pathology." (PMID 35615401, 2022). "In the non-tumor aspect, PCAT19 has been found to play a role in the occurrence of neuropathic pain by targeting the mir-182-5p–JMJD1A axis." (PMID 35480331, 2022). "Referring to the existing literature, PCAT19 is an oncogenic lncRNA that promotes tumor progression through multiple mechanisms, similar to CARD8-AS1." (PMID 34654454, 2021). "Conversely, overexpressing PCAT19 reduced tumor size in mouse xenograft models." (PMID 39744012, 2024). "Interestingly, PCAT19 demonstrates a dual nature, acting as both an oncogene and a tumor suppressor depending on the cancer type." (PMID 39744012, 2024). "In PCa, PCAT19 is significantly upregulated in tumor samples." (PMID 39744012, 2024). "Similarly, in CRC, ROC analysis shows that PCAT19 effectively distinguishes between tumor and normal tissues with high sensitivity and specificity (AUC = 0.940), highlighting its clinical utility in CRC diagnostics." (PMID 39744012, 2024). "Furthermore, PCAT19-long interacts with HNRNPAB to activate a subset of cell-cycle genes associated with PCa progression, thereby promoting tumor growth and progression." (PMID 39744012, 2024). "Moreover, PCAT19 low‐expression patients had smaller tumor size and lower pathological grade, which indicate lower tumor burden and better prognosis." (PMID 36992525, 2023). "Correspondingly, overexpressing PCAT19 reduced tumor size in mouse xenografts." (PMID 36992525, 2023). "The PCAT19-long isoform interacts with HNRNPAB to activate a subset of cell-cycle genes associated with PCa progression, such as CHEK1 and AURKB, while the PCAT19-short isoform possesses potential tumor suppressive function." (PMID 37215575, 2023). "Furthermore, we analyzed the clinical features of LC patients with different expression levels of PCAT19 and discovered that tumor size and pathology were related to the expression of PCAT19." (PMID 35615401, 2022). "The effect of PCAT19 on tumor growth was detected in a tumor-bearing model of nude mice." (PMID 35615401, 2022). "In our study, the overexpressed PCAT19 markedly impacted the tumor cell behaviors." (PMID 35615401, 2022). "PCAT19 could play a role in many vascular diseases that depend on the proliferation of endothelial cells, as well as in tumor angiogenesis, which is crucial in supporting cancer growth." (PMID 36384122, 2022). "All these results indicate that PCAT19 has a certain influence on tumor progression." (PMID 35095999, 2021). "As shown in this figure, the lncRNA PCAT19 and CARD8-AS1 were positively associated with both tryptophan metabolism and MDSC infiltration, suggesting that their immunosuppressive role in the tumor microenvironment is potentially mediated by promoting immunosuppressive metabolism." (PMID 34654454, 2021). "Tumour stage significantly associated with the expression of LINC00673 (p = 0.005), LINC01929 (p = 0.002), PCAT19 (p = 0.001), FENDRR (p = 8.33 × 10–6), SVIL-AS1 (p = 0.037), LANCL1-AS1 (p = 8.69 × 10–7), LINC00968 (p = 2.32 × 10–7) and ADAMTS9-AS2 (8.29 × 10–6) as determined by Kruskal–Wallis test." (PMID 32020063, 2020).
tumor (continued). "Moreover, tumor formation experiments also verified that overexpression of PCAT19 suppressed tumor growth while promoting tumor cell apoptosis, indicating that regulation of PCAT19 expression could regulate the progression of LC." (PMID 35615401, 2022). "The interaction between PCAT19 and miR-142-5p leads to the upregulation of MELK, which has been found to enhance tumor cell proliferation, invasion, and resistance to apoptosis." (PMID 39744012, 2024). "The expression level of onco-lncRNAs, including PCAT19, MALAT1, and NEAT1, and the tumor suppressor lncRNA, CASC2, was increased and decreased, respectively, in PCa patients compared to the healthy group (P < 0.05)." (PMID 37251950, 2023). "This favors accumulation of the long PCAT19 isoform that interacts with HNRNPAB and promotes the expression of cell cycle genes that subsequently fuel tumor growth and metastasis." (PMID 34449663, 2021). "Subsequently PCAT19-long isoform interacts with HNRNPAB and thus influences expression of cell cycle genes leading to acceleration of tumor growth and metastasis." (PMID 34449663, 2021). "Additionally, MeRIP-qPCR assays validated that SOCAR and SNHG8 transcripts were hypermethylated, and PCAT19 and COLCA1 transcripts were hypomethylated in LUAD tumor tissues." (PMID 37029420, 2023). "On the other hand, for PCAT19, FENDRR, LANCL1-AS1, LINC00968 and ADAMTS9-AS2 the median expression level was significantly higher in T1 compared to T2 (p-values ≤ 0.001) and in T1 compared to T3 stage tumours (p-values ≤ 0.01)." (PMID 32020063, 2020). "Similarly, in CRC, PCAT19 is downregulated in both metastatic and non-metastatic tumor tissues compared to normal tissues." (PMID 39744012, 2024). "Further analysis of PCAT19 found that the expression of PCAT19 was significantly correlated with the histological grade (TMN), age, and tumor grade of LUAD, showing a significant negative correlation." (PMID 35095999, 2021). "The low expression of PCAT19 was significantly correlated with the tumor histological grade (MNT), age and tumor stage, showing a significant negative correlation (p < 0.05)." (PMID 35095999, 2021).
cancer (13 papers, 2017 to 2024). A tumor composed of atypical neoplastic, often pleomorphic cells that invade other tissues. "We chose three known cancer-associated lncRNAs (ADAMTS9-AS2, FGF14-AS2 and PCAT19) whose Affymetrix id can be found in this tool to perform the survival analysis over the four cancer types included in the Kaplan-Meier Plotter." (PMID 28389669, 2017). "Expression of PCAT19, its prognostic value, and diagnostic relevance in various cancer types." (PMID 39744012, 2024). "By exploring the molecular mechanisms and pathways associated with PCAT19, we aim to provide a comprehensive understanding of its multifaceted roles in human health and disease, highlighting its potential as a therapeutic target for cancer and pain management." (PMID 39744012, 2024). "In addition, a cancer-associated SNP located within the intronic region of the lncRNA PCAT19 has been found to regulate the isoforms of PCAT19 in a reciprocal manner." (PMID 33499210, 2021). "Understanding the regulatory mechanisms and pathways of PCAT19 is crucial for developing targeted therapies for cancer and pain management." (PMID 39744012, 2024). "Overall, the dysregulation of PCAT19 across multiple cancer types, its correlation with key clinicopathological parameters, and its prognostic and diagnostic significance underscore its clinical value." (PMID 39744012, 2024). "Recent studies have detected dysregulated expression of PCAT19 across various human cancer specimens." (PMID 39744012, 2024). "PCAT19 shows significant clinical value, impacting clinical features, prognosis, and diagnosis across multiple human cancers." (PMID 39744012, 2024). "Abnormal expression of PCAT19 has been observed in various cancers, and its correlation with clinical features and prognosis positions it as a promising prognostic biomarker." (PMID 39744012, 2024). "Overall, the widespread abnormal expression of PCAT19 across various cancer types suggests a crucial role for PCAT19 in tumorigenesis and development." (PMID 39744012, 2024). "We discuss the mechanisms by which PCAT19 influences cancer progression and its potential as a therapeutic target." (PMID 39744012, 2024). "This consistent pattern of dysregulation in both tissue specimens and cell lines underscores the potential importance of PCAT19 in cancer biology." (PMID 39744012, 2024). "The transcriptional regulation of PCAT19 needs to be clarified, since it has been reported in cancer cells, and we report its enrichment in healthy endothelial cells." (PMID 36384122, 2022). "This multi-compartmental presence indicates that PCAT19 may serve diverse functions within the cell, contributing to its complex role in cancer pathology." (PMID 39744012, 2024). "This work compiles current research on PCAT19’s involvement in cancer pathogenesis and progression." (PMID 39744012, 2024). "Recent studies have highlighted the critical role of PCAT19 in the progression of this cancer." (PMID 39744012, 2024). "The expression of PCAT19 was also investigated in several cancer cell lines." (PMID 39744012, 2024). "This upregulation suggests that PCAT19 may play a oncogenic role in the progression or maintenance of these cancer types." (PMID 39744012, 2024). "PCAT19 is a multifaceted lncRNA with significant roles in both cancer and neuropathic pain." (PMID 39744012, 2024). "The PCAT19/miR-182/PDK4 axis regulates cell proliferation by modulating glycolysis and mitochondrial respiration, promoting the Warburg effect—a metabolic hallmark of cancer." (PMID 39744012, 2024). "LncRNA PCAT19 has been demonstrated to be involved in tumorigenesis in multiple types of cancer." (PMID 36992525, 2023). "Compared with normal breast epithelial cells, PCAT19 expression level was lower in cancer cells." (PMID 36992525, 2023).
cancer (continued). "Besides, using bioinformatic methods, we proposed several ceRNA regulatory axes possible for PCAT19 to exert cancer‐suppressing ability." (PMID 36992525, 2023). "qRT-PCR was performed to detect the expression of PCAT19 in cancer tissues and ANT collected from 74 LC patients, and the results exhibited that PCAT19 was conspicuously downregulated in tissues of LC patients (P < 0.001), with the mean PCAT19 expression level being 4 ± 1.2." (PMID 35615401, 2022). "Although we provide data on the differential expression of PCAT19 in vascular diseases and in cancer endothelial cells, exactly how PCAT19 is involved in these diseases is so far unknown." (PMID 36384122, 2022). "Next, it was checked whether PCAT19 expression differed specifically in the endothelial cells that formed a cancer compared with healthy endothelial cells." (PMID 36384122, 2022). "Presence of the cancer-predisposing alleles facilitates promoter-to-enhancer switching, leading to reduced binding capacity of the transcription factors NKX3.1 and YY1 to the promoter of the short isoform of the PCAT19 (Prostate Cancer Associated Transcript 19) lncRNA transcript." (PMID 34449663, 2021). "Previous studies also confirmed that PCAT19 could regulate the progression of other cancers." (PMID 35095999, 2021). "Similarly, fibroblast-like cancer cells (C10) and endothelial cell-like cancer cells (C11) were identified based on the specific expression of fibroblast markers (DCN, COL1A2 and COL6A3) and endothelial cell markers (PCAT19, VWF and PLVAP)." (PMID 36451812, 2022). "A handful of studies have characterized some of the PCATs in more detail, one of which reported the importance of PCAT19 in the development of cancer, but did not address its physiological function in health." (PMID 36384122, 2022).
PCAT19 also shares sentences with these, for which no sentence is quoted: lung adenocarcinoma (2 papers); acute myeloid leukemia (1); adenocarcinoma (1); colorectal cancer (1); large cell carcinoma (1); laryngeal tumor (1); liver cancer (1); osteosarcoma (1); respiratory diseases (1); thyroid cancer (1).